BCL2 (BCL2 apoptosis regulator)
Diseases named in the same sentence as BCL2 in open-access papers (continued):
Sharing a sentence is not in itself a finding about the gene and the disease.
tumor (continued). "Ubenimex inhibits the expression of the proto-oncogene, Pim-3, which is accompanied by decreased expression of BCL-2 and BCL-XL, decreased phosphorylation of Bad, and increased tumor apoptosis." (PMID 29069816, 2017). "Immunohistochemical tests were applied to detect the expressions of Bcl-2, Bax, HIF-1α, and VEGF in tumor tissues." (PMID 29348766, 2017). "Together, miR21 increased interaction of Treg cells with endothelial cells via ICOS/ICOSL axis and stimulated tumor angiogenesis, which was interrupted by ABT-199 through targeting Bcl-2 expression on endothelial cells." (PMID 28637496, 2017). "In another study, the Bax/Bcl-2 ratio was statistically correlated for CRC against age and tumor location." (PMID 28253296, 2017). "After four cycles of NCT, Tumor progression was noted in six patients, all of whom had HER2-negative/Tau-positive/Bcl-2-positive tumors." (PMID 29254147, 2017). "The Bcl-2/Twist1 complex, compared to either Bcl-2 or Twist1 alone, is more efficient in promoting EMT and tumor metastasis in OSCC." (PMID 28032603, 2017). "Consistently, decreased Bcl-2 expression, increased cytochrome c and PARP level, and activated caspase-3 and caspase-9 were observed in the tumor samples." (PMID 28567017, 2017). "The expression of genes involved in the apoptosis process (BCL2 and BAX) by HepG2 and HL-60 tumor cells treated with CR-LAAO was evaluated by RT-qPCR." (PMID 28205610, 2017). "Paraffin-embedded tumour samples were reviewed by a single pathologist and tested for immunohistochemistry (IHC) expression of Ki-67, ERCC1, Bcl-2, and Lin28a." (PMID 28955403, 2017). "Of the 14 tumor tissues with positive p65 expression, 6 were positive for MYC and 9 were positive for BCL-2." (PMID 28039454, 2017). "We found that the depletion of Bcl-2/Twist1inhibited OSCC cell migration, invasion and EMT both in vitro and in a Tca8113P160 derived tumor model." (PMID 28032603, 2017). "The protein expression level of Bcl-2, BAX and Caspase-3 in tumor tissue was analyzed by Western Blot." (PMID 28514759, 2017). "We also demonstrate that high BIM protein expression positively correlated with increased sensitivity to the PI3K/mTOR and BCL-2/BCL-XL inhibitor combination, consistent with an ex vivo tumor slice study of single-agent ABT-737 treatment." (PMID 28848242, 2017). "Immunohistochemical staining showed that tumor cells were positive for CD20, CD79a, and BCL2 expression." (PMID 28122582, 2017). "We found that the pro-survival protein BCL2 is selectively induced in the niche-protected tumor cells following lapatinib treatment, and combined inhibition of HER2 and BCL-2/XL enhanced targeting of these residual tumor cells." (PMID 28649658, 2017). "Meanwhile, the expression of Bcl-2 was decreased but the expression of the BAX and Caspase-3 was increased in tumor tissue." (PMID 28514759, 2017). "Our investigations further highlighted that concomitant disruption of BTK and Bcl-2 with sub-IC50 doses of ibrutinib and venetoclax, respectively, synergistically induce tumor cell lethality in WT and ibrutinib-resistant cells." (PMID 28548645, 2017). "In vivo, Salicylate ●Phenanthroline Copper (II) Complex administration significantly attenuated tumor growth of MDA-MB-231 xenografts, and the expression levels of Bcl-2, Bcl-xL and survivin were reduced as measured by immunohistochemical staining." (PMID 28415735, 2017). "Immunohistochemical stainings of cyclin E, MCM2, VEGF, CDC6 and BCL2 were performed in tumor tissues, and the staining intensities of cyclin E, MCM2, CDC6 and BCL2 were decreased in the GBK treatment group in xenograft-tumor mice compared to the control group." (PMID 28467790, 2017).
tumor (continued). "Since ABT-737 targets both BCL-2 and BCL-XL, we investigated the contribution of both of these anti-apoptotic proteins to tumor cell viability by using specific inhibitors as single agents and in combination with GNE-493." (PMID 28848242, 2017). "While clinical inhibition of BCL-2 has been achieved with the BH3 mimetic venetoclax, anti-tumor efficacy is limited by compensatory induction of MCL-1." (PMID 29269870, 2017). "Use of selective inhibitors of BCL-2, BCL-XL, and MCL-1 allowed us to examine the relative dependence of these proteins on pro-survival activity of the PDX tumor cells." (PMID 28848242, 2017). "In other words, the present study supported that the Bcl-2/Twist1 complex, compared to either Bcl-2 or Twist1, is more efficient in promoting EMT and tumor metastasis in OSCC." (PMID 28032603, 2017). "Immunohistochemically, the tumor cells were positive for CD34, bcl-2 and STAT6, whereas alpha-SMA, desmin, and S-100 were negative." (PMID 28063145, 2017). "Double-hit lymphomas (DHL) are rare high-grade neoplasms characterized by two translocations: one involving the gene MYC and another involving genes BCL2 or BCL6, whose diagnosis depends on cytogenetic examination." (PMID 28061782, 2017). "In follicular colonization, the tumor cells (CD20+, Bcl-2+, CD10−, and Bcl-6−) colonize the reactive follicles composed of dendritic cells (CD21+, CD23+) with distorting the original follicular structure." (PMID 28353588, 2017). "With the increase of 18F-FDG radioactive concentration, the expression level of Bcl-2 and Survivin decreased and Bax and Caspase-3 increased significantly compared with control group, indicating that therapeutic doses of positron could induce tumor cells apoptosis in a dose-dependent manner." (PMID 28881676, 2017). "Collected the tumor tissues were subjected to western blot showed decreased protein expression of pSTAT3 ser727, total STAT3, Bcl-2, Bcl-XL, FAS, cyclin D2, MMP2, and MMP9 in metformin treated vs. control mice." (PMID 28114390, 2017). "Furthermore, a compound targeting Bcl-2/Bcl-XL may have anti-tumor activity." (PMID 28863158, 2017). "A B-cell associated signature distinguished HPV(+) from HPV(−) tumors, and included the DEGs CD200, GGA2, ADAM28, STAG3, SPIB, VCAM1, BCL2 and ICOSLG; the immune signal relative to T-cells was qualitatively similar between TILs of both tumor cohorts." (PMID 27462861, 2016). "Recent studies have suggested the existence of at least two subgroups within tumours with an amplification on the HER2-locus, expressing high or low levels of the ESR1, GATA3 and BCL2 gene cluster." (PMID 27341628, 2016). "Downregulated factors such as MGMT, p16Ink4A, p27Kip1, Bcl-2, Bax, Bcl-x, and MT3 are involved in the cell cycle, apoptosis, tumor suppression, metabolism, and enhanced TMZ sensitivity." (PMID 27893664, 2016). "It is shown that ectopic expression of anti-apoptosis proteins, such as BCL2 and XIAP, confers tumor cells with resistance to apoptosis, leading to an increase of macroscopic metastasis." (PMID 27329720, 2016). "Tumor cells are CD34, CD99, and bcl2 positive, while the S-100 protein, actin, and desmin are negative." (PMID 27579199, 2016). "Pre-clinical studies show that venetoclax has significant anti-tumor activity in AML models and that venetoclax-dependent inhibition of Bcl-2 can prime AML cells for responsiveness to chemotherapy." (PMID 27353420, 2016). "In vivo experiments confirmed that ANRIL promoted EOC tumor growth in part by decreasing P15INK4B and increasing Bcl-2 levels." (PMID 27095571, 2016).
tumor (continued). "These include the oncogene MDM2 and various genes supporting cell proliferation (KI-67), apoptosis (Bax), tumor invasion and metastasis (MMP9) and tumor angiogenesis (VEGF), as well as the anti-apoptosis gene BCL-2." (PMID 26943040, 2016). "In our in vitro studies we observed potent anti-tumor activity of selinexor in MYC and BCL2/6 “double-hit” DLBCL, while the clinical responses were observed across all subtypes of NHL independent of genetic abnormalities." (PMID 27693556, 2016). "miR-195 can suppress tumor cell proliferation and metastasis by targeting several proteins, including BCOX1, BCL-2, and CARMA3." (PMID 27126129, 2016). "Treatment with a specific inhibitor of Bcl-2, ABT-199 (also known as Venetoclax) at 1 μM, EDIL3-mediated anoikis resistance and anchorage-independent tumor growth were completely blocked." (PMID 26735172, 2016). "BDA-366 was previously shown to disrupt the noncanonical BCL2-BH4-BAX interaction, inhibit the binding of BCL2 with IP3R and enhance Ca2+ release and apoptosis in tumor cells." (PMID 27049723, 2016). "Results demonstrated that Bcl-2 dependent NB-1643 had an immediate tumor response to both ABT-199 alone and to the combination of ABT-199 and CPM, with measurable tumor regression at the end of treatment." (PMID 26874859, 2016). "Immunohistochemical staining revealed that tumor nodules originating from A2780-KD1 and A2780-KD2 cells had decreased ki67, increased P15INK4B, and decreased Bcl-2 expression compared to nodules originating from A2780-NC cells." (PMID 27095571, 2016). "The anti-apoptotic genes BCL2, MCL1 and A20 are regulated in tumour cells by imiquimod, allowing the onset of apoptotic pathways." (PMID 27936237, 2016). "Herein siRNA used against BCL2 inhibited tumour growth, especially in the LPH-PolyMet-siBCL2 treatment group, which provided persistent suppression of tumour growth." (PMID 27264609, 2016). "We observed that Bcl-2 expession (anti-apoptotic factor) decreased in tumours treated with MRS1220-Vc (17% less) and on the other hand vincristine alone increased Bcl-2 expression." (PMID 27634913, 2016). "They contribute a lot to tumor initiation and development by controlling the expression and function of tumor suppressor genes, including K-RAS, ELK1, MYO6, BCL2, ERK5 and IGF1R." (PMID 27626488, 2016). "Since the MYC pathway promotes apoptosis via the intrinsic BCL2- dependent pathway, it is reasonable that the regulation of this survival pathway is both necessary and sufficient for the GCB tumor survival." (PMID 27102442, 2016). "Intriguingly, in accordance with the tumour suppressive functions of USP16, USP16 depletion was capable of inhibiting P21 expression but increasing Bcl-XL and Bcl-2 expression in Huh7 and PLC/PRF/5 cells." (PMID 27633997, 2016). "The tumour exhibited a CD20+, CD79a+, CD 10+, immunophenotype, Bcl-2 focal positivity, Ki-67 >90% positivity, whereas other markers were negative including CD3, CD45RO, CD15, CD30, ALK and EMA." (PMID 26990772, 2016). "Subsequently, the ratio between BCL-2 and Bax was decreased, and the activity of caspase-3 was increased, which led to the apoptosis of DOX-resistant tumor cells." (PMID 27731405, 2016). "More importantly, Bit1 downregulation significantly lowered Bcl-2 and MMP-2 levels in EC9706 xenografted tumor tissues, meanwhile triggered apoptosis after treatment with different doses of Bit1 shRNA." (PMID 26956728, 2016). "Role of microRNA-182 in posterior uveal melanoma: regulation of tumor development through MITF, BCL2 and cyclin D2." (PMID 32309578, 2016). "BCL2 BH4 domain also binds to calcineurin, CED-4, HIF-1α, c-Myc, paxillin, Raf-1, Ras and VDAC, promoting tumorigenesis or tumor survival and contributing to both anti-apoptosis and pro-tumorgenesis activities of BCL2." (PMID 27049723, 2016). "Immunohistochemistry (IHC) of MYC, BCL2 and BCL6 was performed on tumor samples from 114 patients with PCNS-DLBCL." (PMID 27286976, 2016).
tumor (continued). "The tumours highlighted the overexpression of MYB (fold‐change increase = ×2.04), BCL2 (fold‐change increase = ×2.34) and BIRC3 (fold‐change increase = ×3.93)." (PMID 26969893, 2016). "Immunobloting analysis of tumour tissues showed that platycodin D enhanced the expression of FOXO3a, p21, p27, Bax and cleaved PARP, while decreased the expression of MDM2, Bcl‐2, cyclin B1 and D1 and CDK‐1, ‐2, ‐4 and ‐6." (PMID 26648178, 2016). "Based on the results of our study, we inferred that PDK1 protected BCL-2, BCL-xL, and PI3K/Akt/mTOR from degradation and that the persistent stabilization of these proteins made the tumor cells resistant to apoptosis, thus conferring survival advantages." (PMID 26593251, 2016). "In a xenotransplanted tumor model of human endometrial cancer in nude mice, increased PAX2 expression was observed in tumors with poor cell differentiation, and tumor volume as well as expression of PCNA and Bcl-2 were decreased following knockdown of PAX2." (PMID 27764784, 2016). "This characterises TrkAIII SH-SY5Y cells as type I tumour cells, sensitive to TRAIL-induced apoptosis through the extrinsic pathway, with the intrinsic pathway blocked by constitutive Bcl-2, Bcl-xL and Mcl-1 expression (this study and 49)." (PMID 27821809, 2016). "Consistently, previous studies have revealed multiple targets for miR‐16 including BCL2, CCND1 and WNT3A 17, 18, 19, 20, which are involved in tumour cell apoptosis or cell‐cycle regulation; and thus, directly regulate tumour growth." (PMID 27241533, 2016). "Given the therapeutic efficacy of BL-EI001 in our in vivo model, we examined the caspase 3, Bcl-2, Bax and p-ERK1/2 expressions in tumor samples Immunoreactivity." (PMID 25742792, 2015). "For better understanding of the mechanism of the therapeutic efficacy of BL-AD008 in our in vivo model, we examined the caspase-3, caspase-8, Bcl-2, Bax, p-AMPKα and ZIPK expressions in tumor samples immunoreactivity." (PMID 25797270, 2015). "Immunohistochemically, the tumor revealed strong and diffuse staining for CD34, bcl-2, and vimentin, and a high mitotic index (seven mitoses per 10 high-power fields)." (PMID 25649645, 2015). "Based on the immunohistochemical analysis of tumor sections, we observed a high expression of Bax in the cancer FALHE-treated group and a high expression of Bcl-2 in the cancer control group." (PMID 25996383, 2015). "Inhibition of Bcl-2 molecules using BH3-mimetic drugs has shown a significant reduction of cell proliferation and tumor growth." (PMID 25690034, 2015). "To find out the anti-tumor mechanism of SCL on H22 tumor-bearing mice, we examined the impact of SCL on the anti-apoptotic factor Bcl-2 and the pro-apoptotic factor Bax using immunohistochemical analysis." (PMID 26426041, 2015). "Small-molecule BH3 mimetics such as ABT-737, ABT-263 (navitoclax), and ABT-199 (venetoclax) have been used extensively to elucidate the functions of BCL-2 and BCL-XL in tumor and normal cell survival." (PMID 25590800, 2015). "Aukema and colleagues defined DHL as a neoplasm characterized by a MYC rearrangement combined with another genetic abnormality, such as BCL2, BCL3, BCL6, or other genes." (PMID 26515759, 2015). "In both patient groups, Bcl-2 expression strongly correlated with positive ER/PR status, low grade, negative human epidermal growth factor receptor 2 (HER2) status, and small tumor size, as previously reported." (PMID 26472348, 2015). "In summary, we showed that HNHA had more potent anti-tumor activity than the established HDAC inhibitors SAHA and TSA with induction of apoptosis through expression of Bcl-2 and engagement of the mitochondrial pathway in RCC cells in vitro and in vivo." (PMID 25613585, 2015). "In the current study, the down-regulation of Bcl-2 in PC3-KLK10 cells and xenograft tumour tissue shifted our focus on the mitochondria." (PMID 26616394, 2015).
tumor (continued). "The relative mRNA expression levels of Bax, Bcl-2, VEGF, HIF-1α, and survivin in the tumor tissues were determined by real-time PCR." (PMID 25629230, 2015). "Inhibition of AXL reversed chemoresistance by decreasing expression of the anti-apoptotic proteins BCL-2, BCL-XL, MCL1 and survivin in tumor cells and activated pro-apoptotic proteins BAD, BAX, BCL-2, BAK and PUMA." (PMID 26328272, 2015). "We also observed increased apoptosis in G31P treated tumor using TUNEL staining, supported by immunoblotting analyses of apoptotic proteins such as PARP, Caspase-8, BAX, and Bcl-2." (PMID 26087179, 2015). "RES has been shown to counteract tumor growth of MCF-7 breast cancer cell line in vitro, by down-regulating Bcl-2 expression and suppressing NF-κB activity." (PMID 25918934, 2015). "Levels of BCL-2 were reduced by ca 40% in tumours from MM41-treated animals relative to controls, consistent with BCL-2 being a target for MM41." (PMID 26077929, 2015). "Western blots of BCL-2 protein and k-RAS enzyme for four animals show a consistent pattern of reduction in protein levels for all four treated tumours that were examined, compared to controls." (PMID 26077929, 2015). "In the present study, the data revealed that the compounds Ad23 and Af23 suppressed the phosphorylation of FGFR1 in H460 tumor tissues, thereby inhibited the downstream phosphorylation of ERK and AKT, and reduced the expression of BCL-2, COX-2, and Cyclin D1." (PMID 25880284, 2015). "Related proteins such as Bcl-2 and HK-2 were down-regulated and KLK10 was up-regulated in the PC3 cell line and xenograft tumour." (PMID 26616394, 2015). "Previous studies have confirmed that tumor markers, including CD34+, Bcl-2+ and CD99+, are generally positive in SFT cases, which has aided the diagnosis of SFTs." (PMID 25452776, 2015). "Immunohistochemically, tumor cells were diffusely positive for vimentin and CD99, focal positive for CD34, bcl-2 and Actin." (PMID 26155787, 2015). "We found that in tumor cell lines with low or mutant KEAP1, and in Keap1-/- murine embryonic fibroblasts, multiple KEAP1 targets including NRF2, IKKβ, and BCL2 were elevated." (PMID 26301506, 2015). "Bcl-2 overexpression in ABC-DLBCL patients treated with CHOP regimens have poor prognosis, probably due to the tumor cells’ ability to resist apoptosis induced by chemotherapy." (PMID 26475474, 2015). "Effects on BCL-2 and k-RAS protein expression in treated tumours are reported, together with data on cellular localisation." (PMID 26077929, 2015). "The present study finds that levels of the BCL-2 and k-RAS proteins are both reduced in treated tumours relative to untreated control tumours and apoptosis is induced, providing correlative evidence that these genes are targets of MM41 in vivo." (PMID 26077929, 2015). "Immunohistochemical examination revealed the presence of numerous tumor markers, including CD99+, Bcl-2+, partial CD34+, focal S-100+, SMA+ and CD68−." (PMID 25452776, 2015). "For example, RRM2 plays an important role in regulating expression of the anti-apoptotic protein Bcl-2 and reveal a critical link between RRM2 and Bcl-2 in apoptosis signaling and tumor developing." (PMID 26596768, 2015). "The immunohistochemical characteristics of the engrafted tumours, i.e. overexpression of the proteins CD20, CD10, and Bcl2, were similar in both rituximab- and vehicle-treated mice." (PMID 25977881, 2015).